IL4R (interleukin 4 receptor)
Diseases named in the same sentence as IL4R in open-access papers (continued):
Sharing a sentence is not in itself a finding about the gene and the disease.
tumor (continued). "Finally, qPCR helped investigate the Rab1A/IL-4Rα mRNA expression in 24 tumor and normal tissue cases." (PMID 37117331, 2023). "When injected along with anti-IL-4Rα aptamer-conjugated SPIONs to tumor bearing mice, these two NMs significantly decreased tumor size comparing to control or single NM-treated animals, indicating that simultaneous functional blockade of these targets potentiates antitumor activity." (PMID 35463298, 2022). "Furthermore, a histologic analysis of the tumor tissues confirmed that IL4RPep-1-EVsDiD preferentially targeted IL4R-expressing cancer cells." (PMID 36009525, 2022). "In tumor tissue, IL-4R presented a decrease in tumor tissue, which could mean that IL-4 cannot palliate the inflammatory status present in tumor tissue, thus perpetuating it." (PMID 36139645, 2022). "The high levels of IL-4R also promote tumor growth, so targeting IL-4R has been designed." (PMID 36246629, 2022). "Furthermore, tumor tissue stage II showed an increase in IL-4R levels compared to tumor tissue stages I and III." (PMID 36139645, 2022). "Importantly, this time of interaction of tumor cells with IL4rα−/− macrophages, whilst longer than initial intravascular interactions, was significantly shorter than in WT mice, with an average of 84.13 ± 12 min (n = 43, p < 0.0001)." (PMID 36077870, 2022). "Taken together, these results indicate that IL4RPep-1 could selectively target IL4R-expressing tumor (Cal-62) cells." (PMID 36009525, 2022). "Additionally, we isolated tumors, prepared single‐cell suspension, and performed flow cytometry to detect IL‐4R+ tumor cells (CD45− CD11b− CD3− CD124+) and found that DABIL‐4 treatment significantly reduced the frequency of IL‐4R+ cells in tumors." (PMID 33682324, 2021). "In many solid tumors including triple‐negative breast cancer (TNBC), upregulation of the interleukin‐4 receptor (IL‐4R) has been shown to promote cancer cell proliferation, apoptotic resistance, metastatic potential, and a Th2 response in the tumor microenvironment (TME)." (PMID 33682324, 2021). "The type II receptor, comprised of the IL‐13Rα1 and IL‐4Rα subunits, is expressed on tumor cells." (PMID 33682324, 2021). "In addition, as IL4R is highly expressed in human cancers, receptor-directed anti-tumor therapeutic approaches have been tested." (PMID 33419470, 2021). "In conclusion, this study demonstrated that the expression of IL4Rα and IL13Rα1, especially when highly expressed in nuclei, were associated with advanced clinicopathological factors of STS such as higher tumor stage and high histologic grade, and predicted shorter survival of STS patients." (PMID 33419470, 2021). "In-line with these observations, confocal imaging showed obvious cellular accumulations and uptakes of Tat-A1E28 and Tat-A4V48 but minimal accumulations and uptakes of E28 and Tat-E28 in IL-4R expressing tumor cells, which indicated that these enhancements were due to the presence of AP1." (PMID 31952530, 2020). "The therapeutic efficacy of the combined anti-VCAM-1 ssDNA and anti-IL4Rα RNA aptamers in tumor-bearing mice was more pronounced compared with either anti-VCAM-1 ssDNA or anti-IL4Rα RNA aptamer, as assessed by monitoring tumor growth and inhibition using noninvasive BLI and MRI." (PMID 32751068, 2020). "Furthermore, in a lymphoma model, we demonstrated that tumor progression and the accumulation of tumor specific Treg accumulation correlated with the expression of IL4Rα in MDSCs." (PMID 31214178, 2019). "For example, IL4R complex is abnormally over-expressed in malignant ovarian, brain, lung, breast, pancreatic, colorectal, bladder, and other epithelial cell type tumors, suggesting that IL4R complex may be involved for tumor progression." (PMID 31540495, 2019). "Suppression of IL4 and IL13 as well as IL4Rα and IL13Rα1 might be tumor-suppressive especially in poor prognostic group of cancers expressing both IL4Rα and IL13Rα1 as like IL4Rα+IL13Rα1+ subgroup of CCRCC." (PMID 31540495, 2019).
tumor (continued). "Especially, IL4Rα+IL13Rα1+ subgroup of CCRCC significantly associated with larger tumor size, higher tumor stage, and lymph node metastasis, and predicted a 3.2-fold greater risk of death of CCRCC patients compared with IL4Rα−IL13Rα1−/IL4Rα−IL13Rα1+/IL4Rα+IL13Rα1− subgroups." (PMID 31540495, 2019). "In this strategy, the blockade could be achieved either by inhibiting IL-4R or by neutralizing the IL-4 present in the tumor environment." (PMID 28927416, 2017). "Furthermore, there was a significant relationship in both tumor samples and normal tissues between levels of IL-4Rα and NOX1 mRNA." (PMID 28498822, 2017). "IL-4R has been demonstrated previously to be highly expressed on tumor cells and angiogenesis." (PMID 28938600, 2017). "Interestingly, given that IL-4 receptors (IL-4R) are highly expressed in OC and other neoplasia, the IL-4/IL-4R pair has been attempted as a target for OC immunotherapy." (PMID 28966800, 2017). "In addition to cell proliferation and survival, IL-4/IL-4R signal plays a key role in tumor metastasis." (PMID 28927416, 2017). "A combination of pulsed HIFU and atherosclerotic plaque-specific peptide-1 (AP-1)-conjugated liposomes that contain doxorubicin and that specifically bind to the interleukin 4 receptor (IL-4R) worked to elevate the tumor-to-brain drug ratio in a xenografted GBM model." (PMID 26933822, 2016). "Taken together with our observation that apoptotic cells and IL-4Rα have additive effects in promoting tumor growth (and macrophage accumulation), our results are consistent with roles for IL-4/IL-13 in driving NHL-promoting mechanisms independently of apoptosis." (PMID 25702581, 2015). "In addition, intravenous administration of IL-4Rα-lytic hybrid peptide significantly inhibited tumor growth in a xenograft model of human BTC in vivo." (PMID 24868471, 2014). "The expression of TAPBPL, SERPINB9, RCAN1, TMBIM4, JUNB, IL4R, and LY75 is significantly up-regulated in tumor samples with their high expression associated with a poor outcome; the expression of MGST3 is down-regulated in tumor samples with its low expression associated with poor prognosis." (PMID 25133526, 2014). "Similarly, the clinical specimens with advanced tumor grade and clinical stage showed significantly higher levels of IL-4Rα compared to low-grade/stage disease." (PMID 25208941, 2014). "IL-4Rα expression was associated with tumor cells but not infiltrating cells including macrophages or stromal cells." (PMID 25208941, 2014). "Although our ELP-based polymers can target only IL-4R overexpressed cancer cells, many tumor of different origin have been reported to highly expressed IL-4R and thus our designed polymer can be used as a potent drug carrier for various targeted cancer therapies." (PMID 24339977, 2013). "The Fingleton laboratory has previously noted a difference in proliferation and apoptosis indices of IL-4Rα-null versus WT tumours depending on whether tumour growth occurred in a WT or IL-4Rα-null host." (PMID 23784081, 2013). "Additionally confocal imaging results revealed the increased accumulation and uptake of [AP1-V12]6 polymer than [V14]6 control by IL-4R highly expressed tumor cells." (PMID 24339977, 2013). "Lack of IL-13 did not abrogate the effect of absence of IL-4Rα-mediated signalling in DKO animals, thereby refuting the hypothesis that increased tumour initiation in IL-4Rα−/− mice is dependent on IL-13 signalling." (PMID 23784081, 2013). "IL-4Rα chain expression has been demonstrated to be increased in many human cancers including CRC and IL-4R signalling has been implicated in driving tumour growth and metastasis in rodent models of advanced CRC." (PMID 23784081, 2013). "The mechanism(s) by which reduced IL-4Rα-mediated signalling leads to reduced tumour growth remains unclear." (PMID 23784081, 2013).
tumor (continued). "On the other hand, our pre-clinical data demonstrating smaller tumour size on an IL-4Rα−/− background hint that IL-4Rα antagonism could have a therapeutic role in treatment of established CRC." (PMID 23784081, 2013). "The multivalent presentation of the targeting ligand AP1 on the ELP polymer backbone increased binding affinity ∼10000-fold compared to the free AP1 peptide clearly denoted its augmentation in affinity and IL-4R interaction which is important for tumor targeting approach." (PMID 24339977, 2013). "The low level of IL-4Rα on splenic myeloid cells from MT/ret mice, similar to that in negative littermates, is consistent with data in transplanted tumor models indicating that the suppressive function of splenic MDSC does not always involve a high expression of this marker." (PMID 21633700, 2011). "Studies using monoclonal antibody MR6, which is thought to bind to the interleukin-4 growth factor receptor (IL-4R), indicate that IL-4R molecules are upregulated in tumours of epithelial origin and that radiolabelled MR6 is effective as an in vivo tumour imaging agent." (PMID 2736228, 1989). "Notably, combining anti-PD-1 therapy with either a genetic IL-4 KO in tumor cells or with an FDA-approved IL4R-blocking antibody in a clinically relevant OvCa mouse model delayed tumor progression underscoring the translational potential of this strategy as a therapeutic approach." (PMID 39837825, 2025). "Engineered exosomes derived from M1 macrophages, displaying IL4R-targeting peptides and loaded with NF-κB p50 siRNA and miR-511-3p, specifically bind to the IL-4 receptor on TAMs, promoting their reprogramming toward an M1 phenotype, enhancing anti-tumor immunity, and suppressing tumor growth." (PMID 41459510, 2025). "Exposure of the tumor/immune cell co-cultures to the PD-1 blocking monoclonal antibody Pembrolizumab significantly enhanced the effector T-cell activation induced by proinflammatory cytokines and the concurrent blockade of PD-1 and IL-4Rα induced higher CD8+ T-cell activation." (PMID 40091029, 2025). "To characterize the human macrophages in HSC-NOG-hIL-6 Tg mice further, we examined the expression of IL-4Rα in human macrophages, as IL-4 is one of the factors supporting the differentiation of TAMs and expression of the IL-4 receptor is a marker for delineating TAMs in tumor." (PMID 29456539, 2018). "Nevertheless, IL-4Rα-knockdown also rendered the cells more susceptible to IGF-I stimulation, indicating that impaired IL-4 signaling may be compensated by other mitogens abundantly present in the microenvironment of the tumor cells in vivo." (PMID 28350325, 2017). "In addition, the existing IL-4R was closely related to tumor genesis by numerous mechanisms." (PMID 28938600, 2017). "Importantly, IL-4Rα silencing also significantly suppressed tumor growth in vivo." (PMID 28350325, 2017). "Therefore, IL-4R-based tumor targeting drug delivery could be used for the treatment of several tumors." (PMID 28938600, 2017). "However, combined lack of host and tumour IL-4Rα signalling was associated with an increase in AI, as well as a reduction in proliferation." (PMID 23784081, 2013). "In addition, tumor infiltrating myeloid cells express IL-4Rα." (PMID 21633700, 2011). "Various IL-4R-expressing tumour types may have different downstream mediators of IL-4 action." (PMID 15714203, 2005). "Mechanistic studies have elucidated IL-4’s interaction with its receptor, IL4-Rα, triggering upregulation of key anti-apoptotic mediators such as cFLIP, PED, FLAME-1, and Bcl-x(L), thereby facilitating tumor survival and advancement." (PMID 40507238, 2025). "At the same time, hypoxic microenvironment of tumor can also promote the polarization of M2 macrophages by up-regulating the expression of VEGF and IL-4R through HIF-123." (PMID 40404811, 2025).
tumor (continued). "While the IL4R-Abx induced 4T1, LLC, and Panc-1 tumor cell cytotoxicity at higher levels than Ctrl-Abx, it revealed similar cytotoxicity levels and IC50 values in tumor cells compared to Abx." (PMID 38646639, 2024). "IL4R-Abx induced lower levels of cytotoxicity in HEK293 normal cells than Abx and Ctrl-Abx, suggesting preferential Abx delivery to tumor cells over normal cells." (PMID 38646639, 2024). "Upregulation of IL-4/IL-4R signaling in TAMs results in their increased secretion of insulin-like growth factor (IGF-1), which, upon binding to IGF-1 receptor (IGF-1R) on tumor cells, upregulates the PI3K pathway, promoting tumor growth and malignancy." (PMID 38254796, 2024). "Aptamers are synthetic oligonucleotides capable of binding to specific targets; they have been used to target molecules overexpressed on the tumor cell surface, such as nucleolins and CD44, or in the tumor microenvironment, such as IL-4Rα." (PMID 36986798, 2023). "Above results we noticed that IL4R, IL2RB and NAT2, which were differentially expressed in CRC tumor, significantly affect both pathological stages and prognosis of CRC patients, collectively." (PMID 35698180, 2022). "Non-tumor adjacent tissue stages II, III, and IV, showed a decrease in IL-4R levels when compared to stage I. Additionally, stage III also presented lower levels than stage II." (PMID 36139645, 2022). "While we observed a delayed progression of 4T1 tumors in the IL‐4R KO mice, DABIL‐4 treatment was found to reduce spleen weights by only 9% (P = 0.35 vs 20% in WT; P = 0.02 in WT) and tumor weights by only 18% (P = 0.52 vs 52% in WT; P = 0.04)." (PMID 33682324, 2021). "In order to assess the relative degree of direct 4T1 tumor cell killing by DABIL‐4, we established 4T1 TNBC tumors in the mammary fat pads of IL‐4R KO mice and then treated these animals with DABIL‐4." (PMID 33682324, 2021). "In this study, we investigated the tumor-targeting activity of various ELP polypeptides containing IL-4 receptor (IL-4R)-targeting peptides (AP1) based on the size and architecture of nanoparticles in tumor accumulation as well as biodistribution." (PMID 32190533, 2020). "The F4/80+ TAMs present in these tumours represented 10.8 ± 3.3% of all live tumoural cells and expressed FAP, alongside the macrophage/TAM markers CCR2, CD11b, CD14, MHCII, IL4-R and MMR, with a low expression of the dendritic cell marker CD11c." (PMID 30054470, 2018). "To make the nanoparticle selectively accumulate into tumor tissues, we decorated its surface with a high affinity tumor peptide, AP1, which selectively binds to IL-4R." (PMID 28938600, 2017). "Our data show that tumor-released soluble factors are sufficient to induce STAT3 activation, leading to increased expression of IL-4Rα in monocytes." (PMID 27317770, 2016). "MHC-IIlow TAM are found in the most hypoxic tumor regions and express clearly higher levels of M2 markers such as CD124 (IL-4Rα), stabilin-1, CD204 (SR-A), and CD206 (MMR)." (PMID 24723924, 2014). "Azoxymethane-induced aberrant crypt focus (ACF; 6 weeks) and tumours (32 weeks) were analysed in wild-type (WT) BALB/c mice, as well as in IL-4Rα−/−, IL-13−/− and ‘double-knockout’ (DKO) animals." (PMID 23784081, 2013). "Therefore, one hypothesis that requires testing is that reduced AOM-induced tumour growth, after the initiation phase, in IL-4Rα−/− mice is due to increased host antitumour immunocompetence resulting from an impaired IL-4Rα-dependent tumour-driven MDSC response." (PMID 23784081, 2013). "In our study, both IL4R and CXCR4 gene expressions were decreased with tumor progression, whereas both DOK2 and IL2RG gene expressions were increased with tumor progression." (PMID 23451142, 2013). "IL13RA1, in conjunction with IL4R, forms the type II IL4 receptor on tumor cell membranes." (PMID 39941924, 2025).
tumor (continued). "This led to distinct T cell fates in tumours, including myeloid-like T cells with phagocytic capacity driven by orthogonal GSCFR (oGCSFR), and type 2 cytotoxic T (TC2) and helper T (TH2) cell differentiation driven by orthogonal IL-4R (o4R)." (PMID 40804519, 2025). "For example, the inverted cytokine receptor (ICR) of IL-4/IL-7, composed of the IL-4R extracellular domain and the IL-7R intracellular domain, reduces IL-4’s inhibitory effect on CAR-T cells, promoting T cell proliferation and enhancing anti-tumor activity." (PMID 39958351, 2025). "It is suggested that IL4R regulates tumor-promoting functions rather than BMMs recruitment as substantiated by the comparable abundance of monocytes and macrophages in both the mice groups." (PMID 39497943, 2024). "In tumor cells and pro-tumoral M2-type macrophages, the IL4 receptor (IL4R) is upregulated." (PMID 38646639, 2024). "While A86 was composed of a 16-residue sequence designed as an interleukin-4 receptor-specific targeting ligand (IL4RP1, AP1) for the purpose of tumor-specific delivery, the inclusion of Tat ensured the efficient and direct delivery of miRNA genes to the cytosol." (PMID 38802812, 2024). "Genetically engineered Tat-A86, featuring 16 copies of the interleukin-4 receptor (IL-4R)-binding peptide (AP1), Tat for tumor penetration, and an elastin-like polypeptide (ELP) for presenting target ligands and ensuring stability, served as the basis for this delivery system." (PMID 38802812, 2024). "Compared to Abx and Ctrl-Abx, IL4R-Abx more efficiently increased the population of M1-macrophage and CD8+ T-cells and CD8+ T-cell/Treg ratio, while reducing the population of M2 macrophages, MDSCs, and Tregs in the tumor microenvironment." (PMID 38646639, 2024). "Deleting the IL-4 receptor IL-4Rα in early myeloid progenitors significantly reduced tumor burden, whereas deleting it in mature myeloid cells did not." (PMID 39125732, 2024). "To determine whether Th2 polarization was required in CD4+ T cell immunity against breast carcinogenesis, we examined tumor development in K14-Tslptg, MMTV-PyMTtg, Il4r−/− (Tslp-PyMttg Il4rKO) in comparison to Tslp-PyMttg, PyMttg Il4rKO, and PyMttg animals." (PMID 35657353, 2022). "In multivariate analysis age of the patients (OS; p < 0.001, RFS; p < 0.001), tumor stage (OS; p = 0.010, RFS; p = 0.043), T category (OS; p = 0.048, RFS; p = 0.016), and Nu-IL4Rα expression (OS; p < 0.001, RFS; p < 0.001) were independent indicators of OS and RFS." (PMID 35207737, 2022). "This is also consistent with evidence for IL-4R and IL-10R expression in human blood-circulating monocytes and myeloid-derived suppressor cells (MDSC), as well as with contribution of both cell types to tumor angiogenesis." (PMID 35442077, 2022). "This response was specific to IL4 signaling, as IL4 stimulation of BMDMs isolated from IL4Rα−/− mice did not enhance tumor cell transendothelial migration (n = 3, p-value > 0.05)." (PMID 36077870, 2022). "Indeed, myeloid-specific deletion of cholesterol efflux genes ABCA1 and ABCG1 or inhibition of IL-4R signaling, STAT6, or PI3K has been found to significantly impair tumor progression in an ovarian cancer model." (PMID 34876704, 2022). "pIκB, IκB, pIκB/IκB ratio, COX2, PPARγ, IL-4R and IFNγ protein levels were studied in both tumor and non-tumor adjacent tissues in all stages from CRC patients." (PMID 36139645, 2022). "Together, these results show that WT BMDMs promote tumor cell transendothelial migration in vitro while IL4Rα signaling from IL4 (but not other Th2 or Th1 cytokines) in macrophages enhances their activity in this process." (PMID 36077870, 2022). "By contrast, several studies have shown that an anti-inflammatory response, mediated by interleukin-4 receptor expression (IL4R), may promote tumor cell survival and proliferation." (PMID 34681866, 2021).